SESN2 (sestrin 2)
Diseases named in the same sentence as SESN2 in open-access papers (continued):
Sharing a sentence is not in itself a finding about the gene and the disease.
breast carcinoma (13 papers, 2012 to 2025). "In a xenograft model of breast cancer, mango (Mangifera indica L.)polyphenols decreased tumor weight and volume, and this was associated with increased sestrin-2, LKB1, and AMPK levels." (PMID 38396629, 2024). "BA treatment caused a 1.5-fold increase in autophagic flux, whereas breast cancer cells with silenced SESN2 expression showed only a 0.2-fold (p = 0.1) autophagic flux compared to scr siRNA treated cells." (PMID 36611970, 2022). "Sestrin 2 was implicated in radiation-induced death of breast cancer cells by stabilizing the AMPK complex and/or enhancing AMPK expression." (PMID 34784907, 2021). "Our results suggest that in breast cancer cells SESN2 is associated with AMPK, it is involved in regulation of basal and IR-induced expression and activation of this enzyme, and it mediates sensitization of cancer cells to IR." (PMID 22363791, 2012). "In line with the function of SESNs as stress-inducible proteins that regulate the level of ROS, the functional study revealed an overexpression of SESN2 under radiation-induced oxidative stress in a breast cancer MCF7 cell line." (PMID 37284849, 2023). "RNF167 inhibited the activity of mTORC1 by regulating the Lys-63-linked and Lys-29-linked ubiquitination of SESN2 and CASTOR1, which played a significant tumor-suppressive role in colon and breast cancer." (PMID 38304253, 2023). "Preliminary studies indicate the effects of SESN2 on the radiosensitivity of prostate and breast cancer cells." (PMID 36611970, 2022). "We performed SRB assay and clonogenic survival assay to investigate the effect of SESN2 knockdown on the cytotoxicity of BA treatment in the three breast cancer cell lines, MDA-MB-231, MCF-7 and HS578T, under normoxic and hypoxic conditions." (PMID 36611970, 2022). "The SESN2 gene is one of the strongest up-regulated genes after BA treatment in all five investigated breast cancer cell lines." (PMID 36611970, 2022). "Knockdown of SESN2 enhanced BA-induced ROS production, DNA damage, radiosensitivity and reduced autophagy in breast cancer cells." (PMID 36611970, 2022). "Western blot analysis revealed also an increase in SESN2 protein level after BA treatment in all five investigated breast cancer cell lines under normoxic and hypoxic conditions." (PMID 36611970, 2022). "Concerning Western blot analysis, a reduced SESN2 level was also detected after siRNA transfection, and siRNA transfection prior to BA treatment prevented BA-mediated SESN2 induction in all three breast cancer cell lines." (PMID 36611970, 2022). "Our results identified SESN2 as an important target to enhance the radiobiological and anti-tumor effects of BA on breast cancer cells." (PMID 36611970, 2022). "A transcriptome study of breast cancer cells treated with oleanolic acid, which is also a triterpenoid and shows high structural similarities to BA, also identified SESN2 as one of the most up-regulated genes." (PMID 36611970, 2022). "Genes of GADD45 family and SESN2 were up-regulated in all investigated breast cancer cell lines after BA treatment." (PMID 36611970, 2022). "To investigate the importance of BA-induced SESN2 expression, we reduced SESN2 levels via siRNA and analyzed the therapeutic effects of BA in breast cancer cell lines." (PMID 36611970, 2022). "Nevertheless, we found an enhanced radiosensitization of BA-treated hypoxic breast cancer cells when the expression of stress-induced SESN2 is depleted." (PMID 36611970, 2022). "In this study, expression analyses of BA-treated breast cancer cells under normoxic and hypoxic conditions identified SESN2 as one of the most strongly up-regulated genes." (PMID 36611970, 2022). "In our study, BA treatment caused an increase in autophagic flux, and attenuated autophagy after additional SESN2 silencing was accompanied by an increased radiosensitivity of breast cancer cells." (PMID 36611970, 2022).
breast carcinoma (continued). "Additional irradiation of breast cancer cells with 4 Gy induced formation of γH2Ax foci significantly and reinforced the effects of BA treatment and/or SESN2 inhibition." (PMID 36611970, 2022). "The highlight of this study is the identification and characterization of an important target gene, SESN2, to enhance the radiobiological effects (anti-tumor properties) of BA on breast cancer cells." (PMID 36611970, 2022). "Further analyses are necessary to investigate the distinct role of autophagy for radiosensitivity in the context of SESN2 in human breast cancer cells." (PMID 36611970, 2022). "Sestrin 2 knockdown reduced ER stress-induced autophagy and promoted ER stress-induced cell death by activating the mTORC1 pathway in breast cancer cells lines HCC1806 and MCF7." (PMID 34784907, 2021). "Taken together, these results demonstrate that gAcrp inhibits growth of breast cancer cells by suppressing inflammasomes activation, at least in part, via SESN2 induction and AMPK activation-dependent mechanisms." (PMID 32155890, 2020). "The authors of the study hypothesized that SESN2 blocks ionizing radiation (IR)-induced Akt–mTOR signalling and acts as a radiation sensitizer in breast cancer cells." (PMID 37284849, 2023). "Therefore, we investigated the effects of SESN2 knockdown in combination with BA treatment on breast cancer proliferation, clonogenic survival, autophagy, ROS, DNA damage and radiosensitivity." (PMID 36611970, 2022). "However, combined SESN2 knockdown and BA treatment sensitized human breast cancer cells to radiation, enhanced apoptosis, DNA damage and ROS production and inhibited autophagy." (PMID 36611970, 2022). "Therefore, the combined therapy consisting of SESN2 knockdown or inhibition and BA treatment requires further study as a treatment strategy for breast cancer." (PMID 36611970, 2022). "This study emphasizes that sestrin 2 induction mediated by ER stress contributes to tumor cell survival and that targeting sestrin 2 may be a mechanism for enhancing ER stress-induced cell death in breast cancer cells." (PMID 34784907, 2021). "Indeed, it has been reported that SESN2 increases mRNA levels of AMPKα1, β1 and γ1 in breast cancer cells." (PMID 29163816, 2017). "This supports the hypothesis that SESTRIN 2 expression protects breast cancer cells from Mtx-induced cell death by means of inhibiting protein synthesis through inhibition of mTORC1 rather than autophagy induction." (PMID 26930721, 2016). "In addition, we show for the first time that SESN2 blocks IR-induced Akt-mTOR signalling and acts as a radiation sensitizer in breast cancer cells." (PMID 22363791, 2012). "Breast cancer cell lines MDA-MB-231, HS578T and MCF-7 were transfected with 20 nM siRNA against SESN2 under normoxic and hypoxic conditions." (PMID 36611970, 2022). "Collectively, these results reveal that SESN2 induction critically contributes to AMPK activation, ER stress homeostasis, and finally suppression of inflammasomes activation in breast cancer cells." (PMID 32155890, 2020). "This study highlights the pro-survival role of SESTRIN 2 and demonstrates targeting of SESTRIN 2 in breast cancer cells represents a mechanism to potentiate ER stress-induced cell death." (PMID 26930721, 2016).
breast carcinoma (continued). "In this study, we have focused our efforts on investigating the relationship between SESN2 and its interaction with AMPK at the basal level, and in response to IR in breast cancer cells." (PMID 22363791, 2012). "Through immunoprecipitation we observed that SESN2 directly interacted with the AMPKα1β1γ1 trimer and its upstream regulator LKB1 in MCF7 breast cancer cells." (PMID 22363791, 2012). "At the molecular level, the treatment of MDA-MB-453 breast cancer cell line, OVCAR3 ovarian cancer cell line and HeLa cervical adenocarcinoma cell line with nelfinavir and the proteasome inhibitor bortezomib resulted in the upregulation of SESN2 protein." (PMID 37284849, 2023). "Moreover, they have shown that SESN2 mediates IR-induced AMPK expression and facilitates the radiosensitization of breast cancer cells." (PMID 37284849, 2023). "Similarly, adiponectin prevents the development of breast cancer by inhibiting the NLRP3 inflammasome and ERS activation via the SESN2/AMPK axis." (PMID 34741186, 2021). "Adiponectin was reported to bind to receptors on the cell membrane, activate the downstream sestrin 2/AMPK pathway, inhibit ER stress, suppress inflammatory activity, inhibit proliferation, and promote apoptosis in breast cancer cell lines MCF-7, MDA-MB-231, and T47D." (PMID 34784907, 2021). "In addition, we show that SESN2 mediates IR-induced AMPK expression and facilitates radiosensitization of breast cancer cells." (PMID 22363791, 2012).
colorectal cancer (13 papers, 2017 to 2025). A primary or metastatic malignant neoplasm that affects the colon or rectum. "Expression analysis of SESN2 in colorectal cancers revealed its downregulation, with its reduced levels linked to advanced tumour stages marked by vascular invasion, lymph node metastasis, and liver metastasis." (PMID 40361504, 2025). "SESN2 deficiency in human colorectal cancer cells was also associated with decreased susceptibility to chemotherapeutic drugs." (PMID 37284849, 2023). "On the one hand, SESN2 overexpression caused the inhibition of proliferation and induction of apoptosis in colorectal cancer cells, and on the other, the silencing of SESN2 promoted migration, proliferation and attenuated apoptosis in endometrial cancer." (PMID 36611970, 2022). "In colorectal cancer cells, the combination of oxaliplatin and docosahexaenoic acid caused autophagic cell death mediated by endoplasmic reticulum stress and upregulation of sestrin-2." (PMID 38396629, 2024). "Another study showed that Sesn2 knockout in a mouse model where colorectal cancer was induced through dietary administration of dextran sodium sulphate (DSS) led to accelerated tumour growth." (PMID 40361504, 2025). "Several xenograft experiments on colorectal cancer cells showed that SESN2 overexpression dramatically decreased the size and weight of tumours." (PMID 40361504, 2025). "In another study, Seo and colleagues have shown the interaction between 5-fluorouracil (5-FU), a chemotherapeutic agent widely used in the treatment of colorectal cancer, and SESN2 expression." (PMID 37284849, 2023). "The authors elucidated the molecular mechanism behind the potential contribution of SESN2 to counteract colorectal cancer (CRC) via the activation of AMPK, thereby down-regulating the mTORC1 pathway." (PMID 37284849, 2023). "A decreased expression of SESN2 has been showed in human colorectal cancer (CRC) tissues and HT-29, SW480, SW620 and LoVo cell lines." (PMID 37284849, 2023). "SESN2 suppresses migration and proliferation in vitro, and tumor growth in vivo in colorectal cancer." (PMID 32899752, 2020). "Previous studies have shown that SESN2 inhibits EMT in colorectal cancer." (PMID 40661871, 2025). "A reduced expression of SESN2 correlates with a less favorable prognosis in colorectal cancer." (PMID 39759146, 2024). "The potential tumour-suppressing effects of SESN2 in colorectal cancer cell lines, tissue and a xenograft mouse model were speculated by Wei and co- workers." (PMID 37284849, 2023). "Furthermore, in colorectal cancer lentiviral overexpression of SESN2 inhibited proliferation, enhanced apoptosis and reduced clonogenic survival in vitro and suppressed tumor growth in vivo." (PMID 36611970, 2022). "We previously showed that sestrin 2 is abnormally decreased in colorectal cancer (CRC)." (PMID 28525387, 2017). "In breast cancer, SESN2 regulates AMPK subunit expression and modulates responses to ionizing radiation, while in colorectal cancer, it inhibits cell proliferation via AMPK/mTORC1 pathway activation." (PMID 40661871, 2025). "In colorectal cancer, this ubiquitination may be disrupted by dysregulation of the E3 ligase RNF167 and the deubiquitinase STAMBPL1, thereby impairing SESN2-mediated inhibition of mTORC1." (PMID 40361504, 2025). "SESN2 could suppress HIF-1α accumulation and hypoxia response element (HRE)-dependent gene transcription by regulating AMPK-prolyl hydroxylase (PHD) in colorectal cancer cells, showing its antitumor effect." (PMID 31867002, 2019). "Although DHA has been reported to exert an anticancer effect on colorectal cancer via autophagy, it is not yet certain whether DHA induces autophagy via SESN2 activation." (PMID 31337142, 2019).
diabetes (12 papers, 2014 to 2025). "In this study, we aim to elucidate the relationship between SESN2 deficiency and the promotion of EndMT in the context of diabetes-induced endothelial dysfunction." (PMID 39769227, 2024). "This suggests that, in the context of established diabetes, higher SESN2 levels might be linked to increased cardiometabolic risk." (PMID 40433409, 2025). "While certain studies have examined the association between SESN2 gene expression and metabolic parameters in specific populations, the link between circulating SESN2 levels and cardiometabolic risk factors, especially in the context of diabetes, is not well understood." (PMID 40433409, 2025). "Interventions aimed at maintaining sufficient SESN2 levels could provide a novel approach for mitigating cardiovascular risk in patients with diabetes." (PMID 39636755, 2025). "Notably, SESN2 deficiency promoted EndMT, a key process in diabetes-induced cardiovascular complications, as shown by the increased expression of mesenchymal markers and the decreased expression of endothelial markers." (PMID 39769227, 2024). "The differences between our findings and those of other researches on the levels of Sestrin 2 and betatrophin may be caused by various immunoassays, sample size or subject differences, particularly in terms of BMI and diabetes duration." (PMID 39030467, 2024). "Previous studies have shown that diabetes is associated with a deficiency in SESN2 expression." (PMID 39769227, 2024). "Future studies investigating the mechanistic links between SESN2 and glucose, lipid metabolism, and oxidative response may reveal important insights into the potential therapeutic targeting of SESN2 for the management of diabetes and its associated cardiovascular complications." (PMID 39636755, 2025). "Recent investigations have revealed a positive correlation between plasma concentrations of SESN2 and cardiometabolic disturbances in diabetic patients, suggesting a protective role for SESN2 in diabetes and its related complications." (PMID 40433409, 2025). "Future research with more comprehensive medication data, including drug types, dosages, and durations of use, is needed to fully understand the effects of SESN2, specific medications, and cardiometabolic health in individuals with diabetes." (PMID 40433409, 2025). "Experimentally, we have previously shown that SESN2 deletion exacerbates oxidative stress and endothelial cell death in response to ER stress, a mechanism triggered by diabetes that plays a critical role in cardiovascular dysfunction." (PMID 39636755, 2025). "Our findings show that SESN2 levels are significantly reduced in subjects with diabetes compared to healthy individuals, suggesting a preventive role of SESN2 in such conditions." (PMID 40433409, 2025). "Preliminary studies suggest that SESN2 plays a significant role in the development of chronic diseases, such as diabetes, atherosclerosis, cancer, and other conditions." (PMID 39636755, 2025). "SESN2 is a critical player in managing cellular stress, and its levels can change depending on various factors, such as the stage of diabetes, the presence of other health conditions, and which tissues are being studied." (PMID 39769227, 2024). "The study provides novel insights into the molecular mechanisms underlying diabetic cardiovascular complications and identifies SESN2 as a potential therapeutic target for preventing endothelial dysfunction in diabetes." (PMID 39769227, 2024). "Melatonin attenuates fasting- and diabetes-induced hepatic gluconeogenesis by stimulating the SESN2-SHP axis." (PMID 37488285, 2023). "Melatonin ameliorates fasting- and diabetes-mediated induction of hepatic gluconeogenesis via the stimulation of the SESN2-SHP cascade." (PMID 37488285, 2023). "The implications of our findings suggest that SESN2 could serve as a biomarker for the timely detection and assessment of CVD risk in healthy individuals and patients with diabetes and as a potential therapeutic target." (PMID 39636755, 2025).
diabetes (continued). "Future studies aimed at investigating the differences in SESN2 levels at different stages of diabetes may help to shed light on its potential and improve patient outcomes." (PMID 39636755, 2025). "However, in the context of diabetic complications, SESN2 levels were observed to decrease compared to levels in diabetes alone, indicating disease progression." (PMID 40433409, 2025). "Understanding SESN2 in the context of diabetes and its cardiovascular sequelae may open novel avenues for timely interventions and targeted therapies leading to ameliorated outcomes for individuals at risk." (PMID 39636755, 2025). "Some studies show that SESN2 levels are higher in diabetes, while others report a decline." (PMID 39769227, 2024). "Our study investigated the role of SESN2 in the context of diabetes." (PMID 39769227, 2024). "In the early stages of diabetes, SESN2 levels may rise as part of a protective response to oxidative stress, particularly in tissues like the endothelium, where it helps maintain normal vascular function." (PMID 39769227, 2024). "The existing literature on SESN2 in diabetes shows mixed results." (PMID 39769227, 2024). "Mitigation of the CRBN-BTG2-CREBH axis by the melatonin-SESN2-SHP signaling network may provide a novel therapeutic strategy to treat metabolic dysfunction due to diabetes." (PMID 37488285, 2023). "Finally, we highlight certain Sesn2-related conditions, including aging, cancer, diabetes, and ischemic heart disease." (PMID 32010489, 2020). "Sesn2 is also involved in aging, cancer, diabetes, and ischemic heart disease." (PMID 32010489, 2020). "Interestingly, SESN2 is also expressed in endothelial cells and displays a protective function in that it prevents fibrotic injury in diabetes." (PMID 24838122, 2014). "However, as diabetes progresses, this compensatory mechanism could become overwhelmed, leading to reduced SESN2 levels as the disease becomes more established." (PMID 39636755, 2025). "Specifically, the study compares plasma levels of SESN2 in individuals with and without diabetes and examines the association between CVD risk factors and circulating SESN2 levels in both groups." (PMID 39636755, 2025). "These contrasting associations between SESN2 and cardiometabolic parameters in the healthy and diabetic cohorts suggest that the role of SESN2 might be context-dependent and influenced by the presence or absence of diabetes." (PMID 40433409, 2025). "This suggests that as diabetes progresses, SESN2 may no longer be able to keep up with the oxidative damage and inflammation associated with the disease." (PMID 39769227, 2024). "In diabetes, where MGO levels are elevated, oxidative stress is a key contributor to endothelial dysfunction, and the lack of SESN2 exacerbates this process." (PMID 39769227, 2024).